SLTM (SAFB like transcription modulator)
Description:
When overexpressed, acts as a general inhibitor of transcription that eventually leads to apoptosis.
Synonyms: MET; FLJ13213
Tractability: PROTAC: UniProt records ubiquitination sites on it; ubiquitination databases record sites on it; its protein half-life has been measured; a small molecule that binds it is known.
Gene: Protein-coding gene on chromosome 15 (58,879,049 to 58,933,991, reverse strand). Ensembl gene ENSG00000137776.
Subcellular location: Nucleus
Subcellular location (Human Protein Atlas): Nuclear bodies; Nucleoplasm
Gene Ontology:
Molecular function: protein binding; RNA binding; nucleic acid binding
Cellular component: nuclear body; nucleoplasm; nucleus
Genetic constraint (gnomAD): Loss-of-function variants: 37 observed, 109.77 expected, observed/expected ratio (o/e) 0.34, 90% interval 0.26 to 0.44. The upper end of that interval is the gene's LOEUF score, 0.44, which puts it in group 1 of 6, group 1 being the genes least tolerant of losing a copy. Missense variants: 881 observed, 1,144.9 expected, observed/expected ratio (o/e) 0.77, 90% interval 0.73 to 0.81. Synonymous variants: 350 observed, 381.69 expected, observed/expected ratio (o/e) 0.92, 90% interval 0.84 to 1.
Homologues: Orthologues: chimpanzee SLTM (100% identical), macaque SLTM (99% identical), dog SLTM (96% identical), pig SLTM (96% identical), rabbit SLTM (92% identical), mouse Sltm (91% identical), rat Sltm (91% identical), guinea pig SLTM (80% identical), tropical clawed frog sltm (61% identical), zebrafish sltm (54% identical), Drosophila melanogaster Saf-B (26% identical), Caenorhabditis elegans phm-2 (19% identical). Paralogues in human: SAFB2 (34% identical), SAFB (33% identical).
Diseases named in the same sentence as SLTM in open-access papers:
SLTM is named in the same sentence as 5 diseases in open-access papers, as found by Europe PMC text mining. Sharing a sentence is not in itself a finding about the gene and the disease. The quoted sentences say what the papers report.
liver cancer (1 paper, 2024). An epithelial or non-epithelial malignant neoplasm that arises from the liver. "One of the mutations in our study occurred in CTNNB1, one of the most frequently mutated proto-oncogenes in liver cancer, while the other mutation occurred in SLTM, a regulator of RNA processing." (PMID 38497929, 2024).
prostate carcinoma (1 paper, 2023). A carcinoma that arises from epithelial cells of the prostate gland. "With siRNA screens, several of these were indicated in survival (DDX6, EIF4A3, PABPN1), growth (e.g., EIF5A, HNRNPH2, LRRC47, and NVL), and migration (e.g., NOL3 and SLTM) of prostate cancer cells." (PMID 37591798, 2023).
heart disease (1 paper, 2021). "Further potentially disease-relevant protein candidates without a known functional relation to hypertrophy, fibrosis or decompensated heart disease were SLTM, HNRNPLL, FIP1L1, RNMT, KRT18 and PUF60 and the downregulated NUDT4, GCAT, KIDINS220 and ARVCF." (PMID 34937869, 2021).
SLTM also shares sentences with these, for which no sentence is quoted: infection (1 paper); Obesity (1).